G6PD (glucose-6-phosphate dehydrogenase)
Diseases named in the same sentence as G6PD in open-access papers (continued):
Sharing a sentence is not in itself a finding about the gene and the disease.
G6PD deficiency (continued). "From a safety perspective, the sensitivity and negative predictive values of POC G6PD tests to identify G6PD deficient and intermediate cases are critical to minimize adverse reactions to drugs that are contraindicated in individuals with G6PD deficiency." (PMID 37824592, 2023). "Over the past few decades, all developed field applications for diagnosing G6PD deficiency including rapid diagnostic test (RDT) kit provide a qualitative result, which only reliably identifies whether the individual is normal or severely G6PD deficient with less than 30% residual enzyme activity." (PMID 37388931, 2023). "VHVs had knowledge that individuals with G6PD-deficiency should refrain from consuming certain foods, particularly legumes.“Checking [on] G6PD....the doctor said whether to eat or not eat pea for the one with deficiency." (PMID 37438774, 2023). "Infrequent case reports have shown that patients with methemoglobinemia may go on to develop autoimmune hemolytic anemia following methemoglobinemia in the setting of patients both with and without glucose-6-phosphate-dehydrogenase (G6PD) deficiency." (PMID 36225525, 2022). "A study revealed a high prevalence (up to 42.3%) of G6PD deficiency without coding or intronic G6PD mutations in patients suffering from this form of diabetes, although the impact of potential technical issues such as poor storage or degradation of samples cannot be totally ruled out." (PMID 36431166, 2022). "One of the major confounders and a limitation in this study is the inherent disadvantage of G6PD deficiency due to the associated haemolysis, which may be one of the factors that account for the absence of consensus on the G6PD-malaria protection hypothesis." (PMID 35527254, 2022). "Because the newborn’s susceptibility to oxidants (G6PD and pyruvate kinase deficiencies) is usually not known, NF often carries a warning for patients with G6PD deficiency, in whom it may cause haemolytic anaemia." (PMID 35529053, 2022). "The G6PD enzyme activity is in the normal range, which can rule out g6pd deficiency." (PMID 36428936, 2022). "In particular, high levels of G6PD-rich reticulocytes, known as reticulocytosis, commonly observed in newborns may be an important interfering factor for the detection of G6PD deficiency in newborns, leading to false-negative results." (PMID 36419023, 2022). "A very large multi-country genetic association study with over 11,000 severe malaria cases and 17,000 population controls found no overall protective effect of the G6PD + 202T allele (the most common mutation in sub-Saharan Africa causing G6PD deficiency), under an additive model." (PMID 34225842, 2021). "However, in humans with G6PD deficiency, other tissues (e.g., muscle and endothelial cells in the pulmonary artery) have decreased G6PD activity, albeit not as severe as seen in RBCs." (PMID 34138756, 2021). "Another limitation is that the effect of G6PD activity on the risk of aspirin‐induced hemolysis could not be analyzed in our study, because we only preliminarily screened for G6PD deficiency." (PMID 34369077, 2021). "After the enzymatic defect was identified as G6PD deficiency, scientists sought to assess whether RBCs had an all or none effect, or if there was an age-related gradient of G6PD activity." (PMID 33790795, 2021). "Diabetes and the deficiency of glucose-6-phosphate dehydrogenase (G6PD), the major enzyme that catalyzes the first step of the pentose phosphate pathway, have been reported to aggravate each other, and a possible association has been reported between diabetes and G6PD deficiency." (PMID 34026300, 2020). "There are a few previous studies working on if there is an association between the occurrence of malignant hyperthermia and the existence of glucose 6-phosphate dehydrogenase (G6PD) deficiency, and there was no report on growth hormone doping in the literature." (PMID 32832162, 2020).
G6PD deficiency (continued). "Although most G6PD deficiency patients do not show clinical signs and symptoms, it is commonly characterized by abnormally low levels of G6PD, and some variants could be fatal due to complete loss of enzyme activity." (PMID 32316233, 2020). "WHO recommends routine testing of G6PD deficiency prior to primaquine administration; however, in poorly resourced communities this is rarely possible, and hence radical cure is usually prescribed without prior G6PD testing." (PMID 32407682, 2020). "We used routinely collected patient data to compare the overall morbidity and mortality in patients treated with and without PQ without prior testing of Glucose-6-Phosphate-Dehydrogenase (G6PD) deficiency in Papua, Indonesia, where there is a low prevalence of G6PD deficiency." (PMID 33175835, 2020). "To enable the World Health Organization include appropriate G6PD POC diagnostic tests in its list of essential in-vitro diagnostics for use in resource-limited settings, we recommend a wider evaluation of available POC diagnostic tests for G6PD deficiency, particularly in malaria-endemic countries." (PMID 32316233, 2020). "The clinical course of SCD, including the degree of anemia was not milder in G6PD deficiency than in G6PD normal patients but could not be proved to be significantly more severe." (PMID 31703724, 2019). "However, the lack of G6PD level information, inaccurate methods of screening G6PD deficiency, and the uncertainty in the safety of a single versus long-term primaquine dosage pose risk to malaria patients when treat with primaquine." (PMID 31590661, 2019). "One possible explanation is that G6PD deficiency in these ethnically different individuals is associated with other variants not detected using DiaPlexC G6PD genotyping kit and that the observed phenotype could be associated with different G6PD genotypes." (PMID 31525211, 2019). "The absence of G6PD A- mutation in this study could be due to geographical location and the molecular heterogeneity of G6PD deficiency among different populations." (PMID 30918572, 2018). "Once the test is done for G6PD deficiency and status of the patient is known, further checking of G6PD enzyme status might not be necessary during future treatment for a parasitic infection, such as for malaria infection." (PMID 30097005, 2018). "In conclusion, we have conducted a comprehensive newborn screening of G6PD deficiency in a large cohort of population from Guangxi, China, and first established a reliable cut-off value of G6PD activity to distinguish heterozygous females from either normal or deficient subjects." (PMID 29339739, 2018). "The inherent disadvantage of G6PD deficiency due to the associated hemolysis could be one of the factors that account for the absence of consensus on the G6PD-malaria protection hypothesis." (PMID 28382932, 2017). "G6PD assay was not done hence the true prevalence of G6PD deficiency was underestimated." (PMID 29065882, 2017). "In other settings, primaquine may be administered without G6PD testing, putting individuals with G6PD deficiency at risk of severe hemolysis, although the degree of risk will depend upon local G6PD variants and their prevalence." (PMID 28542194, 2017). "This study had several limitations: a small number of patients with a G6PD deficiency; could not obtain data about diseases affecting hematological parameters; and the fluorescent spot test is not a confirmatory test for G6PD." (PMID 27109515, 2016). "The CareStartTM G6PD RDT showed a fair degree of agreement (89.8 %; Kc = 0.278, p < 0.001) and a substantial degree of agreement (95.8 %; Kc = 0.773, p < 0.001) with the reference method in detecting G6PD deficiency at cut-off values of ≤10 and ≤20 % of normal activity, respectively." (PMID 27329471, 2016). "In addition to its perfect sensitivity, the CareStartTM G6PD RDT also exhibits high specificity of no less than 90 % for detecting severe G6PD deficiency." (PMID 27329471, 2016).
G6PD deficiency (continued). "The ability of the CareStartTM G6PD RDT to detect all severely G6PD-deficient patients is strongly supported by the perfect (100 %) sensitivity and absolute negative predictability in detecting G6PD deficiency and excluding falsely normal G6PD activity in individuals testing negative." (PMID 27329471, 2016). "Beyond the good performance in detecting severe G6PD deficiency, the CareStartTM G6PD RDT maintains high sensitivity and specificity of more than 95 % with an almost perfect agreement with the reference method at cut-offs of ≤30 and ≤40 % of normal G6PD activity." (PMID 27329471, 2016). "The administration of a single low dose of 0.25 mg/kg bw primaquine to kill P. falciparum gametocytes is considered unlikely to cause serious toxicity even in people with G6PD deficiency and G6PD testing is not recommended prior to the administration of a single low dose." (PMID 26416229, 2015). "Over the past six decades, since licensure of primaquine for anti-relapse therapy of malaria caused by Plasmodium vivax, safe access to primaquine has been denied by the absence of capacity to diagnose glucose-6-phosphate dehydrogenase (G6PD) deficiency in the impoverished rural tropics." (PMID 26652887, 2015). "Irrespective of the applied test format to determine G6PD status, prolonged primaquine courses are usually reserved for patients with mild to moderate G6PD deficiency and only if appropriate monitoring and facilities are available to respond to severe haemolytic reactions." (PMID 26416229, 2015). "However, this is unlikely to be important, because G6PD A- accounts for 90% of G6PD deficiency in Africa." (PMID 26599634, 2015). "G6PD deficiency testing is not widely available, hence there is understandable reluctance to prescribe primaquine to patients with unknown G6PD status in endemic areas." (PMID 24502194, 2014). "While many genetic association studies at G6PD implicitly assume that one nonsynonymous coding variant has both full positive and negative predictive power for G6PD deficiency trait, this approach belies the considerable allelic heterogeneity present at the locus." (PMID 25201310, 2014). "It appears that although the semi-quantitative test can diagnose severe G6PD deficiency, it is not able to diagnose a substantial proportion of heterozygous G6PD-deficient individuals, who are nevertheless partially deficient, with G6PD activity ranging from 10 to 60% of normal." (PMID 23965028, 2013). "The second most common polymorphism found in this study was the Viangchan variant; 36% (13/36) of healthy G6PD deficient S'tieng, 9% (2/23) of healthy G6PD deficient Kinh and 22% (18/82) of Kinh with haemoglobinuria (35.4% with G6PD deficiency and 2.9% without)." (PMID 19589177, 2009). "Glucose-6-phosphate dehydrogenase (G6PD) deficiency is also frequently associated with the syndrome; however, its role is not determinant, as BWF is frequently described in patients with normal erythrocyte G6PD levels who are receiving quinine for severe malaria." (PMID 16022794, 2005). "Although G6PD testing was not performed in our patient, since delaying antidotal therapy would have been unsafe, the patient’s rapid clinical and biochemical improvement without evidence of haemolysis strongly suggests that meaningful G6PD deficiency was unlikely." (PMID 41503312, 2025). "Intuitively, we hypothesize that Duffy phenotype and G6PD deficiency have an “opposite” effect in Africa: non-black Africans are usually Duffy-positive and the African-type G6PD A– genotype is rarely encountered, while most black Africans are Duffy-negative, some of whom may have G6PD A– genotype." (PMID 41452897, 2025). "Clinically, G6PD deficiency has been linked to increased risk of Hepatitis A and B infections, which may be related to deficient interferon responses in hepatocytes due to insufficient ROS generation by NADPH oxidase, as has been described for Dengue virus infection in G6PD-deficient monocytes." (PMID 38938571, 2024).
G6PD deficiency (continued). "A small cohort study of the weekly primaquine regimen in 18 G6PD-deficient (17 had the 871G>A [Viangchan] variant) and 57 G6PD-normal adult vivax malaria patients in Cambodia suggested that single 45 mg doses may not be safe in the more severe G6PD deficiency variants." (PMID 38319064, 2024). "However, in this form of diabetes, G6PD deficiency is unlikely to be the sole result of the metabolic decompensation, since experimentally-induced hyperglycemia by infusion in subjects with this form of diabetes did not inhibit erythrocyte G6PD activity." (PMID 36431166, 2022). "This resulted in unnecessary increase of treatment cost and potential health risks to individuals with glucose-6-phosphate dehydrogenase (G6PD) deficiency if G6PD testing was not performed prior to the treatment, which could lead to severe acute haemolytic anaemia." (PMID 35505339, 2022). "However, both primaquine and tafenoquine can cause fatal hemolysis in people with G6PD deficiency and should never be prescribed as prophylaxis to anyone with G6PD deficiency or unknown G6PD status." (PMID 36559304, 2022). "The frequency of G6PD deficiency and the selective advantage against malaria had a negative correlation with the latitudes, which was consistent with the report that the incidence of G6PD in China was characterized by a gradient distribution from high in South to low in North." (PMID 36212142, 2022). "Class B G6PD variants were discovered in Yala province, suggesting that anti-relapse medications may result in a moderate to severe hemolytic crisis in the absence of screening for G6PD deficiency." (PMID 36508454, 2022). "The high percentage of indirect hyperbilirubinemia in the Bahraini population may be attributed to the high prevalence of G6PD deficiency, as 46.1% of Bahraini nationals were G6PD deficient, while it affected 3.1% of the non-Bahraini population in this study (P < 0.0001)." (PMID 36119547, 2022). "Besides, we assessed only G6PD deficiency (A−) and did not examine other forms of G6PD polymorphisms that may be present in our population." (PMID 33938598, 2021). "However, the lack of knowledge of the national prevalence of glucose-6-phosphate dehydrogenase (G6PD) deficiency may be one of the constraints to the malaria elimination process." (PMID 32176714, 2020). "However, dispensing of primaquine without reliable G6PD testing could cause severe complications among people who have G6PD deficiency." (PMID 30866940, 2019). "In addition, we found that certain common variants at the locus modulate G6PD activity independent of c.202G>A, and identify among these a role for c.376A>G as a genetic modifier which augments by two-fold the risk of G6PD deficiency state in 202AG heterozygote females." (PMID 25201310, 2014). "Due to the risks associated with radical cure treatment in G6PD–deficient individuals, mass administration of radical cure is not recommended by the WHO without first screening for G6PD deficiency." (PMID 38483975, 2024). "Studies have found that patients with G6PD deficiency have an increased risk of GBM and the upregulation of G6PD in GBM patients does not indicate the poor prognosis." (PMID 39516455, 2024). "In diabetics G6PD deficient subjects had significantly greater IL6 levels, and PWV compared to diabetic subjects without G6PD deficiency." (PMID 37741911, 2024). "While the current study did not explore healthcare providers’ views of reporting G6PD deficiency as a secondary finding on NBS, a US study found that pediatric providers in Ohio supported G6PD screening." (PMID 37092512, 2023). "In the context of Pv radical cure in Lao PDR, all female patients, regardless of their qualitative G6PD test results, receive a PMQ 8-week dosage regimen since the treatment guideline recommends using this for intermediate G6PD deficiency among females." (PMID 35468145, 2022).
G6PD deficiency (continued). "G6PD deficiency has often been considered RBC specific, because, unlike RBCs that cannot synthesize protein, nucleated cells can compensate for decreased G6PD enzyme activity by increasing synthesis." (PMID 34138756, 2021). "G6PD deficiency was evaluated using a qualitative phenotypic method (FST test,) and the effect of G6PD genotypes on risk of NH was not evaluated." (PMID 34618852, 2021). "Although detailed metabolomics of sold organs in humans with G6PD deficiency has not been reported to our knowledge, the decreased PPP in organs from the G6PDMed- mouse is consistent with known mild decreases in G6PD-deficient organs in humans." (PMID 34138756, 2021). "G6PD activities were significantly lower in genetically positive males (with a known pathogenic variant) than genetically negative males, indicating that most genetically negative males may not have G6PD deficiency, further suggesting the high clinical sensitivity of genetic diagnosis." (PMID 34659341, 2021). "The point-of-care G6PD rapid test identified 1814 women as normal and 113 women as deficient (1 sample did not have CSG data), indicating a prevalence of 6·2% for G6PD deficiency using that device." (PMID 34270547, 2021). "Therefore, many investigations have been conducted to find out whether or not ABO blood group antigens, glucose-6-phosphate dehydrogenase (G6PD) deficiency and hemoglobin genotypes are associated with susceptibility, resistance, or severity of P. falciparum malaria." (PMID 32646433, 2020). "The biological assays that detect G6PD enzyme activity during malaria treatment may reflect the level of G6PD deficiency and, therefore, may more accurately assess parasite clearance in the presence of treatment rather than using PCR methodology to determine G6PD deficiency as in this study." (PMID 21092137, 2010). "In July 2004, a WHO technical consultation recommended that, as an interim measure, patients should be screened for G6PD deficiency before being given CPG−DDS, though G6PD-deficient patients should not necessarily be excluded from clinical trials." (PMID 18320064, 2008). "In addition, 3D analysis of a set of three miRNAs (miR-451a, miR-16, and miR-155) was able to differentiate G6PD-deficient individuals from healthy individuals, suggesting that these three miRNAs may serve as potential biomarkers for patients in the nonhemolytic phase of G6PD deficiency." (PMID 38992151, 2024). "The breakdown of cell types among WBC was not significantly different in G6PD deficiency, except for monocytes, which have a decreased percentage among WBC (P<.001, SMD=-0.096), whereas the percentage of basophils was increased in G6PD deficient individuals (P<.001, SMD=0.053)." (PMID 37753082, 2023). "Of the patients with haemoglobinuria, 3.0% (1/33) had reduced CYP2D6 activity, and 5.0% (1/20) had G6PD deficiency, and the difference in the prevalence between CYP2D6 (x2 = 1.29, p = 0.257) or G6PD (x2 = 0.10, p = 0.751) status was not statistically significant." (PMID 35279143, 2022). "Although the FST method is a simple and rapid qualitative method for screening G6PD deficiency, as recommended by the International Committee for Standardization in Hematology (ICSH), it does not well serve the purpose of separating G6PD intermediate from G6PD normal." (PMID 36419023, 2022). "SLD-PQ at 0.25 mg per kg body weight is recommended for MDA targeting Plasmodium falciparum malaria; this dose is considered safe even for G6PD-deficient individuals, and the WHO recommends it may be administered without testing for G6PD deficiency." (PMID 34627346, 2021). "Mendelian randomisation (for example, using glucose-6-phosphate dehydrogenase [G6PD] deficiency, a causal genetic variant for lower haemoglobin concentrations in acute infections) is also not possible, as G6PD deficiency may influence the outcome (survival) via other pathways." (PMID 31442221, 2019).